INS (insulin)
Diseases named in the same sentence as INS in open-access papers (continued):
Sharing a sentence is not in itself a finding about the gene and the disease.
diabetes (continued). "Pancreatic β-cells are sensitive to fluctuations in cholesterol content, which can damage the insulin secretion pathway, contributing to the aetiology of type 2 diabetes mellitus." (PMID 30819824, 2019). "Diabetes mellitus is characterized by chronic hyperglycemia due to defects in insulin production and/or the response to insulin." (PMID 31827572, 2019). "Type 2 diabetes (T2D) is the most common type (90%) of diabetes, characterized by hyperglycemia in the context of insulin resistance and impaired insulin secretion." (PMID 30621076, 2019). "Diabetes mellitus is a growing problem worldwide; however, only 23% of low-income countries have access to insulin, and ironically it costs higher in such countries than high-income ones." (PMID 31798448, 2019). "The upregulation at serine 473 phosphorylation by NS5A HCV genotype 3a suggests that this gene impairs the normal signaling of insulin thus leading towards insulin resistance and Type 2 diabetes mellitus." (PMID 30992506, 2019). "We conducted a cross-sectional study on 19,503 Iranian adults, urban or rural residents, to investigate the status of diabetes treatments in Iran and to assess roles of insulin pen devices in glycemic control improvement compared to insulin vials." (PMID 31461470, 2019). "All episodes will be adjudicated by an independent endpoint committee consisting of diabetes specialists blinded to the individual patient insulin regimen." (PMID 31337371, 2019). "More investigation is needed into the relative contributions of each of these mechanisms to insulin resistance and complications of diabetes." (PMID 30907060, 2019). "Different studies describe that ablation of Dicer in β-cell leads to the onset of diabetes because of impairment in glucose-stimulated insulin secretion (GSIS) and insulin biosynthesis." (PMID 31404962, 2019). "The strongest predictors for poor disease control in T2D were the proxy measures for disease severity including duration of diabetes, presence of microvascular complications, being on insulin therapy and number of antihypertensives." (PMID 31729951, 2019). "Our analyses provide new insights into the use of diabetes medications after insulin initiation among commercially insured U.S. adults, calling for future studies to expand examinations to a more general population." (PMID 30759121, 2019). "Metabolically, diabetes is characterized by rapid defective (type 1 diabetes, T1D) or gradual impairment (type 2 diabetes, T2D) of insulin secretion, leading to increased extracellular glucose and greater reliance on fatty acid oxidation." (PMID 31440740, 2019). "Patients were on insulin, metformin, sulfonylurea and thiazolidinedione for the treatment of previously diagnosed diabetes mellitus." (PMID 31101104, 2019). "Stem cell-derived insulin-producing beta cells (SC-β) offer an inexhaustible supply of functional β cells for cell replacement therapies and disease modeling for diabetes." (PMID 30931946, 2019). "Based on the current pathological and physiological understanding of diabetes, receiving insulin therapy and oral hypoglycaemic agents are the most common medical treatment for the disease." (PMID 31798675, 2019). "Exercise increases systemic insulin sensitivity by improving mitochondrial biogenesis, respiration, content, and density in the skeletal muscles of individuals with diabetes." (PMID 31590292, 2019). "GDM is a kind of diabetes during pregnancy due to the increased severity of insulin resistance and an impairment of the compensatory increase in insulin secretion." (PMID 31557941, 2019). "Despite large regional variation, there is widespread delay of insulin initiation from specialist diabetes healthcare professionals in Central and South-Eastern Europe." (PMID 30993528, 2019). "A novel strategy of closed-loop insulin delivery has recently been developed for diabetes treatment, with products such as Medtronic MiniMed® 670G." (PMID 31159842, 2019).
diabetes (continued). "Both increased patient compliance and exhibiting pharmacokinetics identical with that of subcutaneously delivered insulin make this route of administration very attractive in the treatment of diabetes." (PMID 31210056, 2019). "Out of the 140 individuals with known diabetes, 26 subjects (18.6%) were on insulin therapy, 90 (64.3%) on oral therapy, and 9 (6.4%) on diet." (PMID 31009496, 2019). "Beneficial effects of hypoxia on diabetes, obesity and insulin sensitivity in people who live at higher altitudes 39, in obese subjects 6 and in diabetic rats 40 have been indicated in previous studies." (PMID 30868058, 2019). "Diabetes is a group of metabolic disorder characterized by hyperglycemia resulting from defects in insulin secretion, insulin action or both." (PMID 30871605, 2019). "Oral administration of α-LA has modulated insulin sensitivity in patients with type-2 diabetes mellitus." (PMID 31635029, 2019). "What doctors do not know is that everyday stress and anxiety from life can affect the patient's insulin and glucose function, which can exacerbate their diabetes." (PMID 31485387, 2019). "Type 1 diabetes mellitus (T1D) is a chronic autoimmune disease resulting in the destruction of insulin producing β-cells of the pancreas, with consequent insulin deficiency and excessive glucose production." (PMID 31108850, 2019). "The two groups well matched in terms of age, sex, educational attainment, smoking, drinking, hypertension, insulin use and duration of diabetes (all p > 0.05)." (PMID 31651303, 2019). "Diabetes is distinguished by chronic hyperglycemia with disturbances in the macromolecules’ metabolism as a result of impairments in insulin secretion, insulin action, or both." (PMID 31575072, 2019). "Our data provide a mechanistic explanation for the impaired metabolism and insulin secretion produced by chronic hyperglycaemia and diabetes." (PMID 31171772, 2019). "Teaching insulin management, which is an essential part of diabetes management, to children with type 1 diabetes and their caregivers is a fundamental part of a diabetes treatment plan." (PMID 30905141, 2019). "T1D is caused by the autoimmune destruction of pancreatic beta cells, resulting in a near-total deficiency of insulin secretion, and individuals with this type of diabetes are required to inject insulin." (PMID 30736780, 2019). "Diabetes mellitus (DM) is a metabolic disorder characterized by chronic hyperglycemia due to impaired insulin production from pancreatic beta cells and/or insulin resistance." (PMID 31042755, 2019). "Diabetes is characterized by hyperglycemia resulting from defects in insulin secretion, insulin action, or both." (PMID 31685797, 2019). "Apelin has been highlighted as a naturally occurring peptide which inhibits insulin secretion, decreases glucose levels, increases insulin sensitivity and has a role in the pathogenesis of diabetes related complications." (PMID 31492821, 2019). "Cost and effectiveness analyses were completed on patients (95 V-Go, 113 STO) who had comparable baseline diabetes treatment with 3 or more injections per day including both basal and bolus insulin injections." (PMID 32685581, 2019). "As the average half-life of unmethylated INS DNA is relatively short (a couple hours), it is likely we are missing sporadic beta cell killing happening years before diabetes onset until the peri-diagnosis period when beta cell killing is high." (PMID 31398795, 2019). "We found a greater incidence of hypoglycaemia in patients with type 1 diabetes during DKA management, as compared to patients with type 2 or secondary diabetes, despite lower insulin doses." (PMID 31418117, 2019). "Serum TFF3 levels are downregulated in serum of diabetes mellitus type 1 patients, and the presence of glucose and insulin results in elevated serum levels of TFF3." (PMID 31817054, 2019).
diabetes (continued). "Only a few of our participants used insulin, even though the median duration of their diabetes was long (a median and mean of 12 and 11 years, respectively)." (PMID 31492176, 2019). "Adjusted for sex, diabetes duration, smoking, energy intake, physical activity and mode of insulin administration, we observed that breakfast skipping was associated with reduced odds of achieving good glycaemic control." (PMID 31882789, 2019). "A tertiary care center study reported that handwashing was practiced by only 70% of patients with diabetes, with a significant gap between insulin administration guidelines and current insulin injection practices." (PMID 30974788, 2019). "Insufficient supply of insulin occurring in the course of diabetes leads to hyperglycaemia and the development of diabetes’ complications." (PMID 30987291, 2019). "Diabetes self-management (DSM) refers to that patients take on responsibility for nutrition, physical activities, insulin therapy, and glucose monitoring, to maintain a good metabolic control and reduce diabetes complications." (PMID 31428147, 2019). "Diabetes is a multifactorial complex metabolic disease characterized by impaired metabolism of carbohydrates, lipids, and proteins owing to defects in either insulin action or insulin secretion or both." (PMID 30736780, 2019). "Experimental diabetes was induced with a single intraperitoneal STZ injection which selectively destroys secretion of insulin from pancreatic β-cells." (PMID 31234683, 2019). "At 1 year, after marked weight loss, which was somewhat more after RYGB (p = 0.09), similar improvements in glycemic control, diabetes remission, insulin sensitivity, and beta-cell glucose sensitivity were observed." (PMID 30755673, 2019). "To establish widespread cell therapy for type 1 diabetes mellitus, we aimed to develop an effective protocol for generating insulin-producing cells (IPCs) from adipose-derived stem cells (ADSCs)." (PMID 31341242, 2019). "Diabetes is a complex, chronic illness characterized by a chronic hyperglycemic condition resulting from defects in insulin secretion or insulin action or both." (PMID 31488993, 2019). "Emerging evidence indicates that proinsulin misfolding is not only the molecular basis of mutant INS-gene–induced diabetes of youth (MIDY) but also an important contributor in the development and progression of T2D." (PMID 31311313, 2019). "During the past few years, there have been significant advances in diabetes medications, insulin delivery systems, and glucose monitoring technologies." (PMID 31976334, 2019). "The current analysis evaluates data from the Colombian cohort of insulin-treated patients with diabetes enrolled in the IO-HAT study." (PMID 31584770, 2019). "Previous studies have identified several factors affecting the chance of diabetes remission after bariatric surgery, such as age, HbA1c, insulin therapy, and diabetes duration." (PMID 31747392, 2019). "As STZ induces diabetes by the depletion of insulin-secreting pancreatic beta cells, fasting insulin levels and the functionality of the beta cells (HOMA-beta) were determined for all mice." (PMID 30908533, 2019). "This intelligent guess is made evident by the lower number of correct responses for more specific diabetes treatment questions, which focused on insulin injections, blood testing, foot problems, and hypoglycaemia." (PMID 34040849, 2019). "The literature also suggests, substantially higher prices of new insulin analogues and diabetes medicines and their additional costs to individuals." (PMID 31824316, 2019). "Packer further proposed the potentiation of insulin signaling being instrumental in the precipitation of heart failure among patients with diabetes." (PMID 30961600, 2019). "Based on human studies, iron overload has been postulated to affect insulin secretion and resistance, leading to decreased insulin sensitivity and contributing to earlier complications in diabetes." (PMID 31807124, 2019).
diabetes (continued). "As physical activity enhances insulin sensitivity, increase in physical activity can prevent diabetes both by decreasing insulin resistance and by increasing cutaneous vitamin D synthesis." (PMID 30641861, 2019). "Despite having received lower insulin doses, hypoglycaemia was more frequent in patients with type 1 diabetes (76.9%) than in patients with type 2 or secondary diabetes (50.0%) and in patients with newly diagnosed diabetes (54.6%) (p = 0.026)." (PMID 31418117, 2019). "Impairment of insulin secretion and/or insensitivity to the insulin produced can lead to the disease diabetes mellitus." (PMID 30747102, 2019). "The average BMI was highest in insulin‐treated patients with diabetes (34 kg/m2), intermediate in non‐insulin‐treated patients with diabetes (32 kg/m2), and lowest in those without diabetes (29 kg/m2)." (PMID 31271255, 2019). "Measurement of endogenous insulin secretion using C-peptide provides a gold standard classification of diabetes type in longstanding diabetes that closely relates to treatment requirements." (PMID 30969375, 2019). "Our study found that 1 Chinese app included recording insulin injection, and only 1 app stated its target type of diabetes." (PMID 31464191, 2019). "Our results demonstrate that hnRNP F suppression of Bmf transcription is an important mechanism by which insulin protects RPTCs from apoptosis in diabetes." (PMID 31040360, 2019). "Higher FBG level is due to increase in glucagon to insulin ratio as seen in diabetes, where liver is involved in excess glycogen breakdown and gluconeogenesis." (PMID 31080251, 2019). "The recently published PDM-ProValue Study can be seen as an example of a study focusing on effects of modern digitalisation and integrated personalised diabetes management in patients with type 2 diabetes that are treated with insulin." (PMID 30691463, 2019). "Currently, the available therapy for diabetes comprises insulin and various oral antidiabetic agents namely thiazolidinediones, sulfonylureas and α-glucosidase inhibitors." (PMID 31640743, 2019). "Because insulin is widely used for the treatment of hyperglycemia in patients with either type 1 or type 2 diabetes mellitus, it is urgently needed to clarify its potential role in lung cancer." (PMID 31354621, 2019). "At 26 weeks of diabetes, several metabolic changes were observed including elevated blood glucose, glycated haemoglobin, plasma insulin and plasma C-peptide." (PMID 31798462, 2019). "It seems reasonable to conclude that in the insulin treatment of people with diabetes prandial doses of insulin should take into account the result of pre-meal glycemia as well as the composition and size of meals." (PMID 30871141, 2019). "Although his diabetes improved with an increased dose of insulin, the growth differentiation factor-15 level gradually increased, suggesting that his mitochondrial insufficiency did not improve." (PMID 31630688, 2019). "In line with a previous study, we also found a decrease in insulin requirement in patients with type 1 diabetes mellitus treated with DR-HC, compared to an increase in those patients maintaining conventional GC therapy." (PMID 31252397, 2019). "The predictors for poor control of intermediate diabetes outcomes are measures of disease progression including duration of diabetes, microvascular complications, being on insulin and number of antihypertensives." (PMID 31729951, 2019). "By secreting adipocytokines and increasing plasma concentration of free fatty acid, visceral fat is recently considered to be one of the multifunctional organ, which can interfere with the insulin signal and lead to insulin resistance and diabetes." (PMID 31297161, 2019). "Whatsapp provided a means for instant messaging in most instances (57.3%), contact with diabetes education nurse (32.9%) and consultation with the diabetes team about insulin doses and blood glucose regulation (42.7%)." (PMID 30015620, 2019).
diabetes (continued). "A pilot study conducted on 21 patients with type 2 diabetes mellitus (T2DM) showed that the replacement of modern wheat with Khorasan wheat for eight weeks was able to significantly reduce insulin and glucose levels with respect to modern wheat consumption." (PMID 31779167, 2019). "In this review, we comprised relevant investigations on animal models regarding the use of MO extracts on diabetes and glucose metabolism, including changes in insulin levels if reported." (PMID 31810205, 2019). "In Kenya, food insecure individuals with diabetes were more likely to be on insulin or have had been on insulin compared to their food secure counterparts." (PMID 31693702, 2019). "While insulin is the most efficient glucose-lowering agent, previous research has indicated that a large proportion of diabetes mellitus patients discontinue their insulin therapy due to various factors." (PMID 31692777, 2019). "For instance, it has been found that H2S plays an important role in the regulation of pancreatic beta cell function, insulin resistance, and diabetes complications." (PMID 31178664, 2019). "These factors include longer diabetes duration and increased severity, lower BMI, advanced age, poor glycemic control, and low C-peptide levels (indicating decreased endogenous insulin production)." (PMID 30939855, 2019). "Between 70 and 80% of pregnancies in women under age 45 with pre-existing diabetes were exposed to insulin." (PMID 31775682, 2019). "Hyperglycemia poorly controllable by high-dose insulin was reported prior to the diagnosis of mucormycosis in two patients with diabetes." (PMID 30901836, 2019). "Patients treated with insulin had significantly higher fasting blood glucose, BMI, and HbA1c level as well as diabetes-related microvascular and macrovascular complications and had poorer glycemic control than those treated with oral anti-diabetic drugs." (PMID 31297092, 2019). "6-Shogaol therapy prevented the diabetes-induced changes in insulin staining, and in the area of individual islets, or whole pancreas, composed of insulin-positive cells." (PMID 30805033, 2019). "In the pre-diabetes stage, insulin-resistance-related high blood glucose, dyslipidemia and inflammation increase insulin demand, impelling the β cell expansion to secret more insulin." (PMID 31721726, 2019). "Glipizide is a second-generation sulfonylurea drug that is prescribed for hypoglycaemia in type II diabetes and is known to act by stimulating insulin production and correcting cellular lesions which occur during diabetes mellitus." (PMID 30861059, 2019). "Type 1 diabetes, the immune mediated form of diabetes, represents a prototypical organ specific autoimmune disease in that insulin producing pancreatic islets are specifically targeted by T cells." (PMID 30906293, 2019). "Eight weeks of swimming training potentiates the recovery of femoral neck strength in young rats with severe streptozotocin-induced diabetes under insulin therapy." (PMID 31038563, 2019). "Individuals with PPDM used more diabetes medications than well-controlled patients, and their treatment regimens were more complex, with greater use of prandial insulin." (PMID 30925177, 2019). "The population was largely similar to the general diabetes population receiving insulin, with high baseline HbA1c levels and other comorbidities as demonstrated in large epidemiological studies." (PMID 32685581, 2019). "Over 20% of the patients had a history of diabetes, and half of these patients previously used insulin." (PMID 30742240, 2019). "This study is aimed at estimating the proportion of type 2 diabetes mellitus (T2DM) patients treated with basal insulin (insulin glargine U100) and at evaluating daily insulin dose, treatment pattern, and adherence to treatment of these patients." (PMID 31976334, 2019).